VDR (vitamin D receptor)
Diseases named in the same sentence as VDR in open-access papers (continued):
Sharing a sentence is not in itself a finding about the gene and the disease.
breast cancer (continued). "In a study of 136 patients with primary breast cancer, it was found that women with VDR negative tumors relapsed significantly earlier than women with VDR positive tumors." (PMID 24982636, 2014). "KO240 cells originated from a mammary tumor in VDR-knockout mice, they do not express VDR and are resistant to vitamin D3." (PMID 25460500, 2014). "However, it is a cell type-dependent effect as EGF increases VDR in the rat small intestine and 1α,25(OH)2D3 increases EGFR in BT-20 breast cancer cells." (PMID 24600406, 2014). "Although the majority of human breast cancers express vitamin D receptors (VDR), there have been no demonstrations that 1,25(OH)2D3 modulates gene expression in human breast cancer samples." (PMID 23497279, 2013). "Elevated levels of NCOR1 occur in ERα negative breast cancer cells and in turn attenuate anti-mitotic actions of VDR." (PMID 23098689, 2013). "A clear evidence-based rationale is provided to test calcitriol in combination with astemizole as an adjuvant in the management of VDR/Eag1-expressing breast cancer tumors, regardless of the presence of other molecular markers such as ER, PR or Her2-neu." (PMID 22984610, 2012). "In AA women, four SNPs in VDR - rs12721364, rs2239186, rs886441, and rs11568820 (Cdx2) - but none in CYP24A1 were associated with breast cancer risk at a nominal significance level of 0.05." (PMID 22480149, 2012). "We found that four SNPs in VDR and two SNPs in CYP24A1 had differential associations with breast cancer by race (P for interaction was not more than 0.10)." (PMID 22480149, 2012). "Indeed, by taking advantage of VDR and Eag1 increased expression in a high number of breast cancer tumors, this therapeutic approach could be validated in future preclinical studies and clinical trials of mammary carcinoma or any other malignant neoplasm over-expressing Eag1 and VDR." (PMID 22984610, 2012). "Previous studies on VDR expression and its relationship with breast cancer prognosis indicated a longer disease-free survival in patients with VDR positive tumours compared to those with VDR negative neoplasms." (PMID 22276018, 2009). "Vitamin D receptor (VDR) genotypes may influence cancer risk; however, no epidemiological studies in sporadic breast cancer (BC) or malignant melanoma (MM) have been performed in a southern European population." (PMID 19105801, 2008). "The expression of 1α-hydroxylase, 24-hydroxylase and VDR was investigated in breast cancer specimens (n = 19) and normal breast tissues (n = 10) by immunohistochemistry and/or RT-PCR." (PMID 16280049, 2005). "Loss of CYP27B1 expression and molecular defects may lead to reduced VDR signaling and correlate with disease progression and recurrence in many types of solid tumors such as breast cancer and non-melanoma skin cancer." (PMID 40630116, 2025). "Furthermore, higher vitamin D receptor (VDR) levels correlate with improved prognosis in TAM-treated patients, suggesting that VitD may prevent or reverse TAM resistance in breast cancer patients." (PMID 40699718, 2025). "PTPN3 was also reported in breast cancer by dephosphorylating the epidermal growth factor receptor (EGFR), increasing sensitivity to tyrosine kinase inhibitors, and by regulation of the vitamin D receptor expression and stability, which stimulates breast cancer growth." (PMID 37200868, 2023). "In addition, VDR activation, with vitamin D or the synthetic analogue EB1089, could re-sensitize an antiestrogen resistant MCF7 breast cancer cell line to tamoxifen treatment and reduce the incidence of ER-positive mammary tumors in a preclinical model." (PMID 37583424, 2023). "Considering such results, it is possible that analyzing VDR could be of value in certain subgroups of breast cancer, and in others, it may not have any predictive potential." (PMID 36014861, 2022).
breast cancer (continued). "In four independent databases consisting of a total of 581 ER+ breast cancer patients treated with TAM, higher pretreatment expression of VDR in the tumors was predictive of significantly longer RFS, compared with patients whose tumors expressed lower levels of VDR." (PMID 34069442, 2021). "Vitamin D has been found to induce autophagy in luminal-like breast cancer cells (MCF-7, MDA-MB-453, ZR-75-1) and normal stromal breast cells, mainly by upregulation of MAP1LC31B, Beclin1 and a set of other proteins related, however, the same effect appeared after VDR knockout." (PMID 34638264, 2021). "We identified a cyclic peptide (CSSTRESAC) that specifically binds to a vitamin D receptor, protein disulfide-isomerase A3 (PDIA3) expressed on the cell surface of tumor-associated macrophages (TAM), and targets breast cancer in syngeneic TNBC, non-TNBC xenograft, and transgenic mouse models." (PMID 34060472, 2021). "So It may be used to personalize the adjuvant therapy used in treatment of breast carcinoma as Mastectomies were performed more often on VDR-negative tumors (55%) compared to VDR-positive tumors (41%)." (PMID 33906311, 2021). "Treatment with 1,25(OH)2D induced a VDR overexpression and inhibited MCF-7 cancer stem cells proliferation by Wnt/β-catenin proteins downregulation, demonstrating that vitamin D reverts tamoxifen resistance by inhibiting Wnt/β-catenin pathway in breast cancer cells." (PMID 32560347, 2020). "Whether BRCA1mut breast cancer may be sensitive to RXR modulating drugs and whether this may affect tumor biology or even clinical outcome remains to be determined - with the same applying for VDR, respectively." (PMID 28427429, 2017). "Thus, our data indicate that in the absence of ligand, the VDR promotes breast cancer growth both in vitro and in vivo and that cytoplasmic accumulation of VDR is sufficient to produce this effect in vitro." (PMID 28460457, 2017). "In contrast to our initial hypothesis, we discovered that VDR knockdown inhibited cancer cell proliferation in the absence of vitamin D, suggesting a novel function of the VDR in promoting breast cancer cell growth." (PMID 28460457, 2017). "Whether VDR, RXR or PPARγ are expressed in BRCA1 mutated breast cancer or may even be present in case of triple negativity is not known." (PMID 28427429, 2017). "Increased TCF-7 gene expression in MMTV-Ron VDR−/− tumors and decreased expression in response to 1,25D3 in R7 cells may suggest a mechanism by which VDR mitigates metastatic burden in Ron-overexpressing breast cancers." (PMID 26008979, 2015). "Mammary tumor formation occurred in all study mice regardless of VDR status." (PMID 26008979, 2015). "ER positive cells tend to express higher levels of VDR than ER negative cells and in vitro studies have demonstrated that estrogen up-regulates whereas anti-estrogens down regulate VDR in ER positive breast cancer cells." (PMID 24982636, 2014). "Indeed, VDR knock-out mice are more likely to develop ER- and progesterone receptor (PR)- negative mammary tumors as compared with their wild type littermates, highlighting calcitriol prodifferentiating properties." (PMID 24678876, 2014). "Furthermore, over 90% of human breast cancers express the VDR, which correlates with a longer disease-free interval compared to patients with VDR-negative tumors." (PMID 22984610, 2012). "In EA women, two SNPs in VDR - rs11608702 and rs7975332 (Apa1) - and three SNPs in CYP24A1 - rs912505, rs3787555, and rs2244719 - were associated with breast cancer risk (P < 0.05) but did not remain significant after multiple comparisons were controlled for (data not shown)." (PMID 22480149, 2012).
breast cancer (continued). "Importantly, experimental studies on mammary tumors derived from mice lacking VDR have shown it necessary for vitamin D action as 1,25D3 failed to inhibit cell proliferation and apoptosis in these cells." (PMID 21283672, 2011). "Additionally, VDR-positive cases have also been significantly correlated with HER2-negative cases (p = 0.0238), but this is probably due to the low number of positive cases for HER2 in our series of mammary carcinomas." (PMID 20831823, 2010). "Therefore, vitamin D3/VDR signaling may prevent acquiring a stem-like phenotype by normal mammary gland progenitors and somatic breast cancer cells." (PMID 35328609, 2022). "However results on whether VDR may predict prognosis in breast cancer are not consistent throughout the literature." (PMID 28427429, 2017). "However, the status of VDR may not be universally reduced in breast cancer." (PMID 37074210, 2023). "In another study, 1,25D3 did not affect cell growth in breast cancer cell lines SUM-149 and MDA-MB-231, which have comparable VDR levels." (PMID 28947955, 2017). "Knockdown of VDR by siRNA did not affect the anti-proliferative effects of 1,25D in MCF7 breast cancer cells." (PMID 19863778, 2009). "qRT-PCR analysis of mammary tumors demonstrated increased β-catenin transcriptional activity as judged by enhanced mRNA expression of β-catenin target genes (Cyclin D1, c-Myc, TCF-7, VEGF and MMP7) in the absence of VDR." (PMID 26008979, 2015). "It is well documented that Akt activation plays a crucial role in antiapoptotic actions of IGF-I in breast cancer cells and our initial experiments clearly demonstrated that 1, 25-D3 treatment attenuated the survival effect of IGF-I in parental cell line but not in resistant MCF-7/VDR cells." (PMID 23690781, 2013).
diabetes (171 papers, 2006 to 2026). "Polymorphisms in the VDR gene, particularly rs7975232, have been linked to an increased risk of cardiovascular diseases, hypertension, type 2 diabetes mellitus, and colorectal cancer." (PMID 41264635, 2025). "SNPs of the VDR gene have been implicated in various diseases, including rheumatoid arthritis, diabetes, and malignancy." (PMID 40635160, 2025). "Bone health is affected by diabetes through different mechanisms, among others, and particular attention should be kept towards VDR polymorphisms, Vitamin D, incretins, GLP-2, neurotensin, asprosin, irisin, and TXNIP levels." (PMID 40943066, 2025). "It has been reported that the VDR gene and vitamin D play a significant role in reducing the risk of many chronic diseases, including cancer, autoimmune diseases, diabetes, infectious diseases, metabolic syndrome, and cardiovascular diseases." (PMID 39857837, 2024). "Vitamin D receptor (VDR) gene variants have been associated with diabetes mellitus susceptibility and related complications." (PMID 38882352, 2024). "We aimed to evaluate the association of VDR gene polymorphism (rs2228570) FokI and vitamin D levels with diabetes in adults." (PMID 38812030, 2024). "Though the association between 25(OH)D and vascular complications, as well as their interaction with VDR polymorphisms have been extensively explored, most of them focused on the status of diabetes." (PMID 37845735, 2023). "In the 24th week after the diabetes induction, we observe a reduction in VDR expression in the VitD-deficient rats." (PMID 37391399, 2023). "Circulating vitamin D levels, action and underlying vitamin D receptor VDR genetic polymorphisms have been linked to many common diseases such as obesity and associated pathologies, including diabetes, hypertension and CVS diseases." (PMID 37189820, 2023). "In this respect, many epidemiological studies have compared case and control groups to test possible linkages between VDR polymorphisms and several diseases, including its role in bone biology, renal diseases, diabetes, and other conditions, such as obesity." (PMID 36839157, 2023). "In the context of obesity/metabolic syndrome/diabetes, some studies have evaluated the 25(OH)D serum level relationship with VDR gene polymorphisms." (PMID 36839157, 2023). "Genetic variants in the vitamin D receptor (VDR) gene are associated with type 2 diabetes mellitus (T2DM)." (PMID 36143273, 2022). "Aortic valve calcification was associated with age, long-term dialysis, diabetes mellitus, administration of vitamin D receptor activators, elevated serum calcium levels, and anemia (p < 0.05 for all)." (PMID 35366815, 2022). "The TCR pathway, the vitamin D receptor pathway, and the ER-unfolded protein response were all enriched in these genes, which were linked to the development of diabetes." (PMID 36360783, 2022). "Determining the mechanisms behind this interaction between weight status/diet and VDR action has clear clinical relevance given the strong association of obesity and a western diet with insulin resistance and diabetes." (PMID 35620386, 2022). "Several studies found a correlation between VDR polymorphisms and a higher risk for type 1 and type 2 diabetes mellitus (T1DM and T2DM)." (PMID 35627905, 2022). "In our study, the logistic regression analysis adjusted for body mass index and diabetes revealed that the VDR FokI TT genotype showed an association with increased risk of CVD in the genotypic model (p < 0.05) and in the recessive model (p < 0.05)." (PMID 35955825, 2022). "This study investigated the association between 25(OH) vitamin D, vitamin D-binding proteins, and vitamin D receptor (VDR) polymorphisms in healthy individuals and those with prediabetes and type 2 diabetes mellitus (T2D) from South Africa." (PMID 35956323, 2022). "Haplotype analysis of VDR gene polymorphisms was also carried out in studies of type 1 diabetes mellitus (T1DM)." (PMID 33564343, 2021).
diabetes (continued). "The following search strategy were used: (VDR OR vitamin D receptor) AND (polymorphism OR variant OR mutation) AND (diabetes OR mellitus OR diabetes mellitus)." (PMID 34260520, 2021). "This study aimed to examine the four major VDR polymorphisms: ApaI, TaqI, BsmI, and FokI, plasma concentrations of 25-hydroxy metabolites, and occurrence of such conditions as hypertension, diabetes, obesity, hypercholesterolemia in Polish patients with CVD." (PMID 34578994, 2021). "The aim of present study is to probe the relationship between polymorphism of vitamin D receptor gene (single nucleotide polymorphisms) and type 2 diabetes mellitus (T2DM)." (PMID 34394275, 2021). "Numerous diabetes susceptibility loci, include a region consisting vitamin D receptor gene found in chromosome 12q, have been known using genome wide screens." (PMID 34394275, 2021). "It is also reported that the VDR FokI polymorphism is a genetic risk factor for the development of post-transplantation diabetes mellitus." (PMID 33801744, 2021). "A number of studies have reported an association of VDR polymorphisms with Behçet's disease, diabetes, arthritis, autoimmune diseases, and hypertension." (PMID 32351560, 2020). "The association between the polymorphisms in the vitamin D receptor (VDR) gene and the risk of type 1 diabetes mellitus (T1DM) has been evaluated in several studies." (PMID 32771009, 2020). "Vitamin D receptor (VDR) gene polymorphisms are involved in the gene expression regulation and have been associated with type 2 diabetes mellitus (T2DM)." (PMID 31121922, 2019). "Analysis of both human and mice gut microbiota indicated that VDR influences individual bacterial taxa such as Parabacteroides, which is associated with diabetes." (PMID 30828578, 2018). "Both VDR agonist and Juglone significantly improved diabetes-associated endothelial dysfunction and reduced high glucose-induced endothelial apoptosis." (PMID 29849865, 2018). "We aimed to explore the effects of the VDR agonist on diabetes-associated endothelial dysfunction and the role of Pin1 in this process." (PMID 29849865, 2018). "Some VDR polymorphisms are strongly influencing the susceptibility to diabetes in general: BsmIBB, BsmIBb, and TaqItt polymorphisms are linked to susceptibility of T1DM." (PMID 29113124, 2017). "VDR polymorphisms have been linked to a higher risk for type 1 diabetes mellitus (T1DM) and type 2 diabetes mellitus (T2DM)." (PMID 29113124, 2017). "More and more recent attention has been focused on the possible role of VDR gene polymorphisms in the development of a range of diseases, including diabetes, as well as CAD." (PMID 29108239, 2017). "Several studies showed a correlation between VDR genotypes with risk of obesity, diabetes and metabolic syndrome." (PMID 28811597, 2017). "Bone formation decreased under the diabetes state, while bone resorption increased compared to bone formation; furthermore, in the diabetes population, vitamin D receptor (VDR) gene polymorphism was also closely associated with BMD." (PMID 29190676, 2017). "Similar to diabetes, lower concentration of 1,25(OH)2D is associated with athreosclerosis and coronary artery disease through affecting vitamin D receptor signaling." (PMID 27883024, 2016). "Polymorphisms of vitamin D receptor (VDR) gene have been studied as genetic markers of type 1 diabetes mellitus (T1DM) and some studies have reported associations with autoimmune thyroid disease." (PMID 27011770, 2016). "In this study we observed a higher prevalence of VDR FokI polymorphism in a group of T1DM Brazilian patients with a mean of 7 years of diabetes and 3 years of TD, which presented with persistence of GADA positivity and higher prevalence of TPOA positivity." (PMID 27011770, 2016). "Present study was conducted to determine VDR gene variants among Saudi gestational diabetics (GDM) in Madina, KSA." (PMID 26870091, 2015).